LCE2B (late cornified envelope 2B)
Description:
Precursors of the cornified envelope of the stratum corneum.
Synonyms: LEP10; SPRL1B; XP5
Tractability: No criterion of Open Targets' tractability assessment is met for any kind of drug.
Gene: Protein-coding gene on chromosome 1 (152,686,123 to 152,687,397, forward strand). Ensembl gene ENSG00000159455.
Pathways (Reactome):
Developmental Biology: Formation of the cornified envelope
Gene Ontology:
Molecular function: identical protein binding; protein binding
Biological process: epidermis development
Genetic constraint (gnomAD): Loss-of-function variants: 0 observed, 0.34 expected, observed/expected ratio (o/e) 0, 90% interval 0 to 1.86. That is too few expected variants to judge how well the gene tolerates losing a copy. Missense variants: 175 observed, 143.73 expected, observed/expected ratio (o/e) 1.22, 90% interval 1.08 to 1.38. Synonymous variants: 69 observed, 51.55 expected, observed/expected ratio (o/e) 1.34, 90% interval 1.1 to 1.63.
Homologues: Paralogues in human: LCE2C (95% identical), LCE2D (95% identical), LCE2A (87% identical), LCE1E (74% identical), LCE1F (74% identical), LCE5A (73% identical), LCE1D (72% identical), LCE3D (54% identical), LCE3E (52% identical), LCE3B (51% identical), LCE3C (49% identical), LCE3A (48% identical), and 8 more.
Diseases named in the same sentence as LCE2B in open-access papers:
LCE2B is named in the same sentence as 4 diseases in open-access papers, as found by Europe PMC text mining. Sharing a sentence is not in itself a finding about the gene and the disease. The quoted sentences say what the papers report.
hypopharyngeal cancer (1 paper, 2025). Carcinoma, predominantly squamous cell, arising from the epithelial cells of the hypopharynx. "For hypopharyngeal cancer, GHRH, UCN3, LCE2B, DDC, and PCDHGC5 were upregulated." (PMID 40255484, 2025).
laryngeal carcinoma (1 paper, 2025). Carcinoma that arises from the laryngeal epithelium. "LCE2B regulates vascular lymphatic invasion and correlates with poor survival in laryngeal cancer." (PMID 40255484, 2025).
psoriasis (1 paper, 2017). An autoimmune condition characterized by red, well-delineated plaques with silvery scales that are usually on the extensor surfaces and scalp. "Within the keratinocyte differentiation signature subgroup that is down‐regulated in psoriasis, several genes, such as LCE1B, LCE2B, FLG2, and LOR, are known to be associated with the terminally differentiated keratinocytes (cornecytes) that make up the stratum corneum." (PMID 28008606, 2017).
tongue cancer (1 paper, 2025). A malignant neoplasm affecting the tongue. "The findings revealed that, in comparison to their levels in normal tissues, the genes GAL, GHRH, LCE2B, PCDHGC5, and MT3 were notably upregulated in tongue cancer, while NTS was downregulated." (PMID 40255484, 2025).